CLEC18B (C-type lectin domain family 18 member B)
Description:
Binds polysaccharides in a Ca(2+)-independent manner (By similarity).
Synonyms: MRCL2
Tractability: Antibody: UniProt places it where antibodies can reach, with medium confidence; UniProt predicts a signal peptide or a membrane-spanning region; its Gene Ontology location is reachable by antibodies, with medium confidence.
Gene: Protein-coding gene on chromosome 16 (74,408,631 to 74,424,179, reverse strand). Ensembl gene ENSG00000140839.
Subcellular location: Secreted; Endoplasmic reticulum; Golgi apparatus; Endosome
Gene Ontology:
Molecular function: polysaccharide binding
Cellular component: endosome; extracellular region; Golgi apparatus; sarcoplasmic reticulum; endoplasmic reticulum
Genetic constraint (gnomAD): Loss-of-function variants: 5 observed, 30.89 expected, observed/expected ratio (o/e) 0.16, 90% interval 0.084 to 0.34. The synonymous counts are far from expectation, so gnomAD's model fits this gene poorly and the ratio says little. Missense variants: 26 observed, 284.3 expected, observed/expected ratio (o/e) 0.0915, 90% interval 0.066 to 0.13. Synonymous variants: 16 observed, 91.73 expected, observed/expected ratio (o/e) 0.17, 90% interval 0.12 to 0.26.
Homologues: Orthologues: macaque CLEC18A (96% identical), dog CLEC18C (80% identical), rat Clec18a (79% identical), mouse Clec18a (76% identical), Drosophila melanogaster CG42564 (17% identical), Caenorhabditis elegans scl-23 (15% identical), Caenorhabditis elegans scl-5 (12% identical), Drosophila melanogaster CG8483 (12% identical), Caenorhabditis elegans scl-10 (12% identical), Caenorhabditis elegans scl-14 (12% identical), Caenorhabditis elegans scl-20 (12% identical), Caenorhabditis elegans scl-12 (12% identical), and 36 more. Paralogues in human: CLEC18C (99% identical), CLEC18A (99% identical), CRISPLD2 (23% identical), CRISPLD1 (22% identical), CRISP1 (17% identical), CRISP2 (16% identical), CRISP3 (16% identical), R3HDML (16% identical), GLIPR1L1 (15% identical), PI15 (15% identical), GLIPR1L2 (14% identical), GLIPR1 (14% identical), and 1 more.
Diseases named in the same sentence as CLEC18B in open-access papers:
CLEC18B is named in the same sentence as 2 diseases in open-access papers, as found by Europe PMC text mining. Sharing a sentence is not in itself a finding about the gene and the disease. The quoted sentences say what the papers report.
cancer (1 paper, 2024). A tumor composed of atypical neoplastic, often pleomorphic cells that invade other tissues. "Previous studies have shown that CLEC18B, CLEC12A, and CLEC11A are associated with the development of various cancers." (PMID 38167030, 2024). "In contrast, up-regulation of other members from this superfamily such as CLEC18B, CLEC5A, CLEC4A, and CLEC4L were reported to be associated with development, proliferation, migration, and invasion in cancer cells." (PMID 38167030, 2024).
CLEC18B also shares sentences with these, for which no sentence is quoted: dengue (1 paper).